FGF21 (fibroblast growth factor 21)
Diseases named in the same sentence as FGF21 in open-access papers (continued):
Sharing a sentence is not in itself a finding about the gene and the disease.
diabetes (continued). "Circulating FGF21 has been suggested as a potential biomarker for early detection of metabolic syndrome and type 2 diabetes mellitus in adults." (PMID 35740758, 2022). "FGF21/adiponectin ratio independently predicted the onset of prediabetes and diabetes, with the potential to be a useful biomarker of deterioration in glycemia." (PMID 34321008, 2021). "As a result of preclinical studies, FGF21 has been attracting attention for its potential use as a treatment for metabolic syndromes such as diabetes by increasing insulin sensitivity, improving glucose tolerance, and reducing body weight." (PMID 34071457, 2021). "Basically, there are two main factors, oxidative stress and hyperglycemia, that stimulate FGF21 gene expression in diabetes." (PMID 34233693, 2021). "Previous studies have also shown that circulating FGF21 levels are significantly elevated in type 2 diabetes mellitus (T2DM) patients." (PMID 34660809, 2021). "We reported that FGF21/adiponectin ratio was an independent predictor of glycemic deterioration, including incident prediabetes and diabetes." (PMID 34321008, 2021). "These facts demonstrate a crucial role of NAD+ in the FGF21 protection of EPCs against diabetes‐ or HG‐induced dysfunction." (PMID 33599110, 2021). "Recent studies showed that FGF21 acts as an important inhibitor in the onset and progression of cardiovascular complications of diabetes mellitus (DM)." (PMID 34349728, 2021). "Considering the prognostic roles of FGF21 and adiponectin in diabetes, the relationship between the FGF21-adiponectin pathway dysfunction and diabetes development is unclear." (PMID 34321008, 2021). "The function of FGF21 was originally discovered in 2005 when looking for new drugs for the treatment of diabetes." (PMID 34675822, 2021). "Synergistic therapy of glucagon-like peptide-1 (GLP-1) and glucagon receptors can upregulate the expression of FGF21 and abate renal insufficiency induced by diabetes." (PMID 34675822, 2021). "In general, for patients with cardiovascular disease or diabetes, FGF21 is likely to be a powerful biomarker for predicting MACEs." (PMID 34703671, 2021). "At baseline, FGF21/adiponectin ratio levels increased progressively with the deterioration in glycemic control from normal glucose tolerance to prediabetes and diabetes (p for trend < 0.001)." (PMID 34321008, 2021). "Fibroblast growth factor 21 (FGF21) has received substantial attention as a potential therapeutic agent for diabetes via regulating glucose and lipid metabolism." (PMID 33599110, 2021). "FGF-21 levels in the blood are higher in people with reduced glucose tolerance and diabetes, as reported in previous literature." (PMID 34659937, 2021). "FGF21/adiponectin ratio remained an independent predictor of new-onset diabetes when baseline 2hPG or HbA1c levels were involved in the model (Model 2A and 3A)." (PMID 34321008, 2021). "For example, fibroblast growth factor 21 (FGF21) was reported to not only increase energy consumption and resist diabetes, but also maintain thymus structure and increase the number of thymic T cells." (PMID 34122419, 2021). "Among these molecules, glucagon-like polypeptide 1 (GLP1) and FGF21 have become important drugs for the treatment of diabetes and obesity." (PMID 33588950, 2021). "FGF21 can improve glucose uptake by fibroblasts and adipocytes showing the characteristics of effective treatment of diabetes." (PMID 34675822, 2021). "The involvement of AMPK-mediated signaling in the protective effect of FGF21 in various organs during diabetes or other diseases has been reported 18, 40-42." (PMID 32025205, 2020).
diabetes (continued). "FGF21 administered to animals with diabetes and obesitydecreases their BW and blood glucose/insulin levels, improvesblood lipid profile, and increases insulin sensitivity (Bon-Durant, Potthoff, 2018)." (PMID 33659800, 2020). "By contrast, in mice with both obesity and diabetes, FGF21 reduced serum levels of TG by modulating the lipoprotein catabolism and maintaining the phospholipid homeostasis within adipose tissue." (PMID 33213461, 2020). "Fibroblast growth factor 21 ameliorates diabetes-induced endothelial dysfunction in mouse aorta via activation of the CaMKK2/AMPKα signaling pathway." (PMID 33029194, 2020). "In a mouse model of diabetes, fenofibrate treatment was shown to increase serum Fgf21, resulting in local induction of oxidative stress response genes in the retina and kidney." (PMID 33396512, 2020). "In OVE26 type 1 diabetic mice, Fgf21 mRNA and protein levels were found to be increased in the liver and plasma, leading to protection against the diabetes‐induced aortic fibrosis and inflammation." (PMID 32628815, 2020). "Recombinant fibroblast growth factor 21 (rFGF21) has been shown to be potently beneficial for improving long-term neurological outcomes in type 2 diabetes mellitus (T2DM) stroke mice." (PMID 32012810, 2020). "Multiple studies have been done to determine the relationship between FGF21 and type 2 diabetes mellitus." (PMID 30927227, 2019). "Consistent with this, DNA methylation at the FGF21 locus was elevated and negatively correlated with adipose FGF21 expression in human subjects with diabetes." (PMID 31849831, 2019). "HFD feeding for 12 weeks to induce diabetes increased islet protein expression of FGF21 and the autophagy marker LC3-II relative to the chow diet, as demonstrated by Western blot analysis." (PMID 31121855, 2019). "Epidemiology studies revealed that higher serum FGF21 is an independent predictor of the MetS in Asian individuals and FGF21 levels elevated significantly among prediabetic and diabetic patients and can predict the diabetes development in a Chinese population." (PMID 31582974, 2019). "In conclusion, long-term catecholamine overproduction in PPGL leads to the elevation in serum FGF21, especially in patients with secondary diabetes." (PMID 30959789, 2019). "Our data suggest expanded potential uses of FGF21 for the treatment of vascular diseases in diabetes." (PMID 31511499, 2019). "Our data have important implications for FGF21 as a therapeutic approach for alleviation of endothelial dysfunction in diabetes." (PMID 31511499, 2019). "Collectively, these findings suggest that pancreatic FGF21 is important for promoting insulin expression and secretion, which in turn protect against the progression of diabetes." (PMID 30461198, 2019). "Short-term administration of FGF21 reduces insulin levels in both healthy and db/db mice (diabetes mice)." (PMID 30927227, 2019). "Patients with higher FGF21 concentration were older, had higher incidence of hypertension, diabetes, chronic kidney disease, and heart failure." (PMID 30127382, 2018). "The results showed that FGF21 increased, but diabetes decreased the phosphorylation of Erk1/2 and p38 MAPK." (PMID 29445083, 2018). "FGF21, a hormone-like factor, has been found to be a metabolic regulator and a new direction for the treatment of diabetes and cardiovascular disease." (PMID 30157856, 2018). "Exogenous FGF21 treatment improves glucose homeostasis and prevents hyperglycaemia and diabetes in NZO mice, a model of polygenetic obesity and type 2 diabetes with the characteristic trait of pancreatic beta cell loss." (PMID 29550873, 2018). "FGF21 was shown to protect against diabetes-induced apoptosis via upregulating Akt and PGC1α, and Akt and PGC1α activation contributed to phosphodiesterase-5 inhibitor-induced preservation of mitochondrial function in type 2 diabetic hearts." (PMID 30042676, 2018).
diabetes (continued). "FGF21 levels correlate positively with blood glucose levels, as has been shown in hyperglycaemic and obese New Zealand Obese (NZO) mice used as a model of diabetes, in which plasma FGF21 levels reach approximately 0.8 ng/ml." (PMID 29550873, 2018). "In the Baltimore Longitudinal Study of Aging25, the correlation between FGF21 and renal function was consistent, even after the exclusion of all patients with diabetes (5.9% of 744 participants)." (PMID 30127382, 2018). "Patients with higher serum FGF21 concentrations were older and had higher incidences of hypertension, diabetes, chronic kidney disease (CKD), heart failure, and multiple vessel disease." (PMID 30127382, 2018). "Numerous pharmacological studies have shown that FGF21 regulates glucose and lipid metabolism and demonstrates positive effects in the management of diabetes." (PMID 30068552, 2018). "Emerging evidence suggests that FGF21 is a promising therapeutic target for diabetes and various metabolic disorders." (PMID 30127382, 2018). "The strength of the current study is the adjustment for well-established diabetes risk factors (including liver enzymes), and using comprehensive statistical methods (AUC, NRI and IDI) to explore the predictive utility of FGF-21." (PMID 29021814, 2017). "Previous studies have shown the circulating FGF21 levels to be elevated in impaired glucose tolerance and diabetes." (PMID 28582462, 2017). "Serum FGF-21 concentration was measured in a case-control study comprising of 251 incident diabetes cases and 251 age-sex-matched controls nested within a prospective population-based cohort, the Singapore Chinese Health Study." (PMID 29021814, 2017). "A univariate Cox regression analysis showed that age, diabetes mellitus, history of cardiovascular disease, low IGF-1, high CRP, high glucose, low LDL-cholesterol, J-DOPPS risk score, ARO risk score and high FGF21 were predictive for the all-cause mortality." (PMID 28582462, 2017). "Its beneficial roles in regulating insulin sensitivity and glucose homeostasis make FGF21 a promising therapeutic candidate for the treatment of diabetes." (PMID 28770320, 2017). "Given the linear association, we further estimated for the every 1-log pg/mL increment in FGF-21 levels, the ORs (95% CIs) for diabetes in model 2 were 1.16 (0.90–1.50) in the total study samples, 0.89 (0.52–1.53) in men and 1.53 (1.02–2.29) in women." (PMID 29021814, 2017). "Elevated serum FGF21 was found in patients with higher Body Mass Index (BMI) values, type 2 diabetes mellitus, metabolic syndrome, coronary heart disease, chronic and acute renal dysfunction, hepatitis, liver fatty degeneration and cirrhosis." (PMID 27358750, 2016). "Fibroblast growth factor 21 (FGF21) is regarded as an important metabolic regulator playing a therapeutic role in diabetes and its complications." (PMID 27247947, 2016). "DPP-IV inhibition is an effective treatment for diabetes, and FGF21 has also shown to be effective in lowering glucose levels." (PMID 26635356, 2016). "FGF21 has emerged as a powerful pleotropic regulator of metabolic homoeostasis and potentially represents a new class of therapeutics to treat diabetes and its co-morbidities." (PMID 26635356, 2016). "This implies that the dramatic diabetes-induced down-regulation of plasma FGF21 levels in WT type 1 diabetic mice were comparable to FGF21 deletion in FGF21KO diabetic mice with respect to the whole body glucose and lipid metabolic regulation by FGF21." (PMID 25823710, 2015). "A recent study has shown that FGF21 prevents diabetes-induced cardiac apoptosis by activating the ERK–p38MAPK–AMPK pathway; therefore, FGF21 has been proposed as a treatment for diabetes-related cardiac damage." (PMID 26379627, 2015). "Most human studies investigating serum FGF21 in the state of diabetes simply used fasting or stimulated FGF21 levels." (PMID 26540514, 2015).
diabetes (continued). "The mean age of the 504 study subjects was 58 years, the media diabetes duration was 9 years, and the median level of serum FGF21 was 327.03 ng/mL, with an interquartile range of 190.05–545.55 ng/mL." (PMID 25850006, 2015). "FGF19 and FGF21 are enterohepatic hormones that play important roles in the pathophysiology of diabetes." (PMID 25664662, 2015). "In humans, circulating FGF21 levels are elevated in obese subjects, patients with impaired glucose tolerance, type 2 diabetes mellitus, dyslipidemia, and non-alcoholic fatty liver disease (NAFLD)." (PMID 26594197, 2015). "The anti-diabetes treatment often produced a reduction of circulating FGF21 levels in T2DM patients." (PMID 26226139, 2015). "A recent study of 69 newly diagnosed diabetes subjects demonstrated a positive correlation between serum FGF21 levels and CRP." (PMID 25850006, 2015). "More importantly, FGF21 levels in patients with classic type 1 diabetes mellitus (T1DM)and latent autoimmune diabetes in adults (LADA) are actually lower than that in age- and sex-matched healthy controls." (PMID 26540514, 2015). "This additional analysis provided further confirmation that the FGF19-CYP7A1-BA pathway and FGF21 hepatic expression as well as its circulating levels are indeed dysregulated in diabetes but mostly in patients with severe diabetes." (PMID 25664662, 2015). "The elevation of collagen accumulation and CTGF expression was higher in FGF21KO diabetic mice than that in WT diabetic mice at 2 months after diabetes, indicating that FGF21 deletion accelerated and aggravated diabetes-induced cardiac fibrotic remodelling." (PMID 25823710, 2015). "Further in vivo and in vitro studies are needed to elucidate the essential relationship between FGF21 and LEAD and the underlying detailed mechanism in diabetes." (PMID 25850006, 2015). "Human studies have shown that serum FGF-21 levels were significantly higher in type 2 diabetes mellitus (T2DM) patients relative to healthy controls, and this suggests the possibility of direct positive metabolic effects of FGF-21 in humans." (PMID 26497746, 2015). "Fibroblast growth factor 21 (FGF21) is an important regulator in glucose and lipid metabolism, and has been considered as a potential therapy for diabetes." (PMID 27391008, 2015). "Serum FGF21 levels in CHD patients with diabetes, hypertension, or both are higher than those in patients without these comorbidities." (PMID 26483756, 2015). "The diagnosis of diabetes and liver fibrosis were associated with lower FGF19 levels, while, higher FGF21 levels were associated with hypertension." (PMID 25664662, 2015). "At 1, 2 and 4 months after diabetes onset, the plasma FGF21 levels were significantly decreased in WT diabetic mice compared to controls." (PMID 25823710, 2015). "When the presence of diabetes was defined as the final variable in the conditional logistic regression model with the FGF21 concentration as the continuous variable, FGF21 was significantly involved in the model (P = 0.001)." (PMID 24895642, 2014). "Recent human studies indicated that increased serum levels of FGF21 are found in obese individuals and subjects with metabolic syndrome and type 2 diabetes mellitus." (PMID 24895642, 2014). "When the presence of diabetes was defined as the final variable in the conditional logistic regression model with the FGF21 concentration as the continuous variable, FGF21 was significantly involved in the model." (PMID 24895642, 2014). "Additional studies are needed to gain a better understanding of the mechanisms by which liraglutide induces hepatic Fgf21 production and the role of Fgf21 in social isolation-induced diabetes in KKAy mice." (PMID 24804243, 2014). "We also found that diabetes induced renal lipotoxicity, and the subsequent pathological changes were further enhanced in FGF21-KO mice." (PMID 24349242, 2013).
diabetes (continued). "This indicates that FGF21 induced renal protection against early-stage renal apoptosis and later-stage renal dysfunction due to diabetes, through prevention of lipid accumulation and subsequent inflammation, oxidative stress, and fibrotic effect." (PMID 24349242, 2013). "Administration of FGF21 greatly attenuated diabetes-induced renal inflammation, oxidative stress, and fibrotic effect in FGF21-KO mice." (PMID 24349242, 2013). "Subsequent studies showed that administration of recombinant FGF-21 in rodent models of diabetes and in diabetic rhesus monkeys improved blood glucose and the lipid profile." (PMID 22046277, 2011). "On the other hand, plasma FGF21 levels were associated with adverse lipid profiles including HDL-c, LDL-c and triglyceride (all P<0.05) after adjustment for age, gender, BMI and diabetes mellitus in all CKD subjects." (PMID 21525989, 2011). "Human studies indicate that circulating levels of FGF21 increased in obese individuals, subjects with metabolic syndrome, type 2 diabetes mellitus and coronary heart disease." (PMID 21525989, 2011). "We had previously demonstrated that plasma FGF-21 levels were elevated in patients with type 2 diabetes mellitus (T2DM), and were decreased in response to treatment with rosiglitazone." (PMID 22046277, 2011). "Serum FGF-21 levels in CHD patients with diabetes, hypertension, or both were higher than that of patients without these comorbidities." (PMID 21206918, 2010). "Endocrine FGFs (FGF-19, FGF-21) may also regulate glucose and lipid metabolism, acting as potential biomarkers in diabetes." (PMID 40943671, 2025). "Despite this established link, the associations of FGF21 with low protein intake and all‐cause mortality in our study were independent of adjustments for diabetes status and HOMA‐IR in sensitivity analyses." (PMID 40390366, 2025). "Komorita and other researchers discovered that serum FGF21 levels in MDM patients are significantly higher than in patients with other types of diabetes, suggesting that serum FGF21 could be used for preliminary screening of MDM." (PMID 40520227, 2025). "Overexpression of FGF21 in the liver upregulated the expression of genes involved in fatty acid oxidation, accelerated energy consumption, and reduced fatty degeneration, all of which were beneficial for the treatment of diabetes." (PMID 39819596, 2025). "In addition, serum FGF21 level positively correlated with age, BMI, diabetes and lipid profiles including total cholesterol, triglycerides, high-density lipid cholesterol and low-density lipid cholesterol." (PMID 40356318, 2025). "Meta-regression analyses showed that FGF-21 SMD between NAFLD patients and controls was positively associated with the rate of patients with type 2 diabetes mellitus per study, and this could explain 49.2% of the heterogeneity among studies." (PMID 40465044, 2025). "Because FGF21 biology differs between rodents and humans, future trials will need to verify whether circulating FGF21 or its hepatic release is the dominant AMPK stimulus in people with diabetes." (PMID 40861274, 2025). "Given the important role of diabetes and dyslipidaemia in the development of hypertension, we speculate that FGF21 is also a therapeutic target for hypertension." (PMID 40356318, 2025). "Moreover, FGF21 is increasingly recognized as a promising biomarker for predicting the onset and progression of type 2 diabetes mellitus (T2DM)." (PMID 40426925, 2025). "However, the relationships between the other two proteins and diabetes remain controversial, especially for FGF21." (PMID 38643166, 2024). "Many other literature studies have demonstrated that levels of serum FGF21 may be elevated in individuals with CVD risk factors, including high body mass index (BMI), diabetes mellitus, and hypertension." (PMID 38333506, 2024).